IL6 (interleukin 6)
Diseases named in the same sentence as IL6 in open-access papers (continued):
Sharing a sentence is not in itself a finding about the gene and the disease.
pancreatitis (continued). "Cytokine abnormalities, such as elevation of interleukin 1β (IL-1β), IL-6, IL-8, and IL-10, are involved in pancreatitis and IBD." (PMID 32831829, 2020). "In pancreatic tissue, our group has recently shown that PGC-1α binds to phospho-p65 to repress Il6 gene expression during pancreatitis." (PMID 32961723, 2020). "In agreement with an experimental pancreatitis model in dogs,64 day 0 serum IL‐6 concentration was correlated with higher day 1 serum cPLI concentration, linking lipase‐induced tissue damage and pancreatic lesions with inflammation in dogs with AP." (PMID 32893923, 2020). "Comparable to our data, the GPR55 agonist O-1602 significantly reduced the levels of IL-6 both in plasma and pancreas tissue in mice with cerulein-induced pancreatitis." (PMID 32210914, 2020). "Rats that underwent ischemia and reperfusion (I/R)-induced pancreatitis and were treated with Lex032, a broad serine protease inhibitor, preserved capillary perfusion and showed reduced serum IL-6 and amylase concentrations." (PMID 31727956, 2019). "Plasma IL-6 levels are markedly increased in pancreatitis animals, and inhibition of IL-6 alleviates the formation of edema, inflammatory cell infiltration, and necrosis in cerulein-induced AP." (PMID 31272385, 2019). "Serum HMGB1 and IL-6 significantly increased with L-arginine induction of pancreatitis (95.9 ± 21.7 vs. 18.2 ± 9.7 ng/ml, p < 0.0001; 11.66 ± 2.82 vs. 3.85 ± 0.04 nmol)." (PMID 30733719, 2019). "Pro-inflammatory cytokines, such as TNF-α, IL-6, and IL-1β, that are released during the course of pancreatitis mediate the pathogenesis of SIRS including lung injury." (PMID 29847178, 2018). "In pancreatitis, the inflammatory response is triggered by the production of a series of inflammatory cytokines such as IL-6, IL-1β, and TNF-α." (PMID 29849486, 2018). "In many inflammatory diseases including pancreatitis, activated NF-κB translocates to neucleus and binds to the gene promoters for proinflammatory cytokine IL-6 and monocyte chemoattractant MCP-1, resulting in increased production of IL-6 and MCP-1." (PMID 29270134, 2017). "In a model of rat pancreatitis, mild hypothermia applied for 3 hours reduced plasma IL-6 levels compared to normothermia." (PMID 28759646, 2017). "Of significance for pancreatitis is that a good correlation between the level of IL-6 with the disease severity has been observed in human pancreatitis." (PMID 29270134, 2017). "In our study, the loss of JAM-C also resulted in significantly higher levels of serum TNF-α and IL-6 in experimental pancreatitis." (PMID 26841848, 2016). "IL-6 is a pro-inflammatory cytokine that contributes to the severity of pancreatitis as well as the initiation and progression of PDAC and is primarily released by recruited immune cells, including tumor-associated macrophages." (PMID 27281617, 2016). "The level of IL-6 is an early marker of pancreatitis (24–36 hours after the occurrence of symptoms) and it can be considered as a predictor of disease." (PMID 25298618, 2014). "The ratio of serum IL-6 to sIL-6R was suggested to be useful in distinguishing mild pancreatitis from severe pancreatitis with acute lung injury." (PMID 25673030, 2014). "Results from these two independent studies suggest that the deletion of MK2 most likely ameliorates cerulein-induced pancreatitis in mice by decreasing the production of TNF-α and IL-6, thereby reducing inflammatory injuries caused by these cytokines." (PMID 24705157, 2013). "Proinflammatory cytokines such as TNF-α and IL-6 are involved in the pathophysiological processes of pancreatitis." (PMID 24705157, 2013). "While plasma IL-6 levels strongly peaked at 3 h, IL-10 further increased to reach maximum levels 24 h after pancreatitis induction." (PMID 23110041, 2012).
pancreatitis (continued). "When evaluating the systemic inflammatory response following pancreatitis induction, we found both IL-6 and IL-10 plasma levels to be significantly elevated in the BPD-ligated animals at 3 h and these were still enhanced at 48 h." (PMID 23110041, 2012). "In the present study, plasma levels of TNF-α, IL-1ß, IL-6, and IL-10 gradually increased after induction of pancreatitis, with peak levels occurred after 48 or 72 h." (PMID 23029434, 2012). "Antisera neutralizing endogenous IL-6 inhibit inflammatory hyperalgesia and the orally available, small molecule IL-6 receptor antagonist TB-2-081 reverses pain in a pancreatitis rodent model." (PMID 21951917, 2011). "As compatible with our results,in many studies, IL-6 has been reported as a good predictor for the developmentof pancreatitis after ERCP." (PMID 18670651, 2008). "Surprisingly, basal IL-6 levels inthe patients with post-ERCP pancreatitis positively correlated with basal CRPlevels, but negatively correlated with basal IL-4 levels." (PMID 18670651, 2008). "The enhancement of serum TNFα and IL-6 levels in the patients with ERCP-induced pancreatitis reflects the inflammatory activity." (PMID 18670651, 2008). "The aim of this study wasto investigate the association between early changes (within 24 hours) in theserum IL-2, IL-4, TNFα, and IL-6 concentrations and occurence ofsubsequent pancreatitis complication after ERCP." (PMID 18670651, 2008). "We could observe an upregulation of Il6 mRNA as well as a significant IL-6 release from macrophages under in vitro pancreatitis conditions." (PMID 40560328, 2025). "Emerging evidence underscores the pivotal role of interleukins (ILs) in pancreatitis pathogenesis across the disease spectrum, encompassing both pro-inflammatory mediators (e.g., IL-1β, IL-6, and IL-8) and anti-inflammatory regulators (e.g., IL-10 and IL-37) 24-26." (PMID 41208897, 2025). "We aimed to address whether IL-6 or OSM have an impact on the significantly increased numbers of CD4+ T cells during the course of pancreatitis." (PMID 40560328, 2025). "In line with these pro-stress effects, we demonstrated that prolonged cer-pancreatitis led to a significant reduction in acinar cells viability, accompanied by a gradual elevation in the expression of TNFα and IL-6 in response to pancreatitis-mimicking induction in vitro." (PMID 38927047, 2024). "In recent years, IL-6 and IL-17A have become hot research topics, with several studies suggesting that they are involved in the process of AP and can be used in clinical practice to predict the severity of pancreatitis." (PMID 39296668, 2024). "However, loss of Tbx3 leads to overshoot proliferation of acinar cells, accumulation of fibrosis, and enhanced inflammatory stimuli, Il6-Jak-Stat3, and acinar cell-specific NF-κB signaling during pancreatitis." (PMID 36941669, 2023). "Serum concentrations of pro-inflammatory cytokines, such as tumor necrosis factor α, and interleukins, such as interleukin-1 beta (IL-1), interleukin-6 (IL-6), and interleukin-8 (IL-8), were significantly higher in severe pancreatitis compared with mild pancreatitis." (PMID 36979645, 2023). "In addition, upregulation of the ADAM17/IL-6 transsignal/STAT3 axis is a feature in patients with pancreatitis." (PMID 36969002, 2023). "Furthermore, PARP inhibitors have demonstrated effects on reducing pro-inflammatory mediators in the plasma such as TNF-α, IL-1β, IL-2, IL-4, IL-6, IL-12, IP-10, and KC on in vitro models of pancreatitis as well as in vivo models of wound healing injuries." (PMID 33663560, 2021). "In a mouse model of pancreatitis, oral administration of lysine also decreased the plasma concentration of IL-6, malonaldehyde, and nitric oxide, and increased the key antioxidant enzymes superoxide dismutase, catalase, and glutathione peroxidase in the pancreas." (PMID 34445459, 2021).
pancreatitis (continued). "In addition, IL-6 exerts an anti-inflammatory role in a pancreatitis model by regulating the generation of cytokines, expression of adhesion agents, and activation of neutrophils." (PMID 34646877, 2021). "By taking into account our previous studies, in which the plasma levels of IL-6 increased in the PGC-1α KO mice with pancreatitis, we considered studying whether NF-κB and STAT3 activation are involved in inducing Nos2 in the liver upon PGC-1α deficiency." (PMID 32961723, 2020). "IL-6 levels which could be induced by TNFα and IL-1β, are elevated in pancreatitis and serve as markers of the severity of pancreatitis." (PMID 32587518, 2020). "The importance of pro-inflammatory cytokines in pancreatitis has been highlighted by a recent study in 84 patients with AP who were screened for known polymorphisms in TNFα, interleukin 1 (IL-1), IL-1 receptor antagonist (IL1RN), IL-6, and IL-10." (PMID 30681551, 2019). "For example, in male WBN/Kob rats, TNF-α and IL-6 concentrations peak well before the peak of disease severity what may suggest that both these proteins are involved in the onset of pancreatitis." (PMID 31624954, 2019). "However, no study has yet determined the effect of DHA on the serum levels of amylase, lipase and IL-6 in the models of cerulein-induced pancreatitis." (PMID 28704954, 2017). "DHA may prevent pancreatic injury by suppressing the expression of IL-6 in cerulein-induced pancreatitis." (PMID 28704954, 2017). "To test whether the inhibition of NF-κB by the PKD inhibitor altered expression of inflammatory molecules in pancreatitis, we examined pancreatic level of cytokine IL-6 and chemokine MCP-1." (PMID 29270134, 2017). "IL-6 also plays an important role in the development of pancreatitis." (PMID 27281617, 2016). "However, recent studies discovered that IL6 is involved with other gastrointestinal related disease phenotypes including pancreatitis, polycystic liver disease, salivary glands, congenital diarrhea, pancreatic agenesis and gallbladder disease." (PMID 25933025, 2015). "The major findings were that 14 out of 47 cytokines were higher on admission in patients who developed severe pancreatitis compared with those with moderately severe or mild disease and that IL-6 and hepatocyte growth factor (HGF) were independent predictors of severe acute pancreatitis." (PMID 25673030, 2014). "Furthermore, QYT effectively decreased the levels of TNF-α, IL-6 and IL-8 in patients with pancreatitis, indicating that QYT functions by downregulating the expression of TNF-α." (PMID 25371738, 2014). "Furthermore, in a pancreatitis model, polyamines could prevent damage to membrane structure caused by activated oxygen radicals by preventing the production of TNF-α and IL-6 production." (PMID 40141396, 2025). "Notably, multiple inflammatory mediators, i.e., IL-17, IL-6 and IL-10 as well as IL-12 and IL-15 have been shown to play a main role in the pathogenesis of pancreatitis, and their serum levels have been reported to correlate with disease severity in AP patients." (PMID 38910880, 2024). "Therefore, the consumption of lycopene-rich foods may prevent the development of alcohol/LPS-associated pancreatitis by activating Nrf2-mediated expression of NQO1 and HO-1, thereby downregulating ROS-mediated IL-6 expression in pancreatic acinar cells." (PMID 35326169, 2022). "Therefore, in this study, we aimed to determine the effect of lycopene on IL-6 expression to investigate whether lycopene supplementation is beneficial in preventing alcohol/LPS-induced pancreatitis by activating antioxidant mechanisms." (PMID 35326169, 2022). "Likewise, serum levels of circulating IL‐6 cytokine were elevated after 8 hours of pancreatitis." (PMID 34132031, 2021). "Therefore, DHA may help prevent the development of pancreatitis by suppressing the activation of NF-κB and PKCδ, expression of IL-6, and oxidative damage to the pancreas." (PMID 28704954, 2017).
pancreatitis (continued). "The mechanism by which L-lysine exerts an anti-inflammatory effect may be inhibition IL-6 expression, a key regulator of inflammatory mediator expression, as an early event in experimentally induced pancreatitis, which correlates with the inflammatory response." (PMID 26100532, 2015). "Immunofluorescence staining for cytokines and ST6GAL1 revealed that ST6GAL1 was co-expressed with IL-1β and IL-6 in the epithelial cells of PDAC and pancreatitis tissues." (PMID 39260693, 2024). "The levels of inflammatory cytokines, especially proinflammatory cytokines such as IL-6, IL-1β and TNF-α, which are indicators of severity in pancreatitis, are also important." (PMID 38698325, 2024). "Our study conducted in human samples also identified the role of IL-6 and TNF-α in developing pancreatitis." (PMID 38533139, 2024). "Compared with the normal pancreas, elevated levels of IL-1β and IL-6 were observed in the PDAC and pancreatitis specimens." (PMID 39260693, 2024). "Specific inflammatory cytokines, such as IL-6 and TNF-α, are used to detect inflammation in many cystic conditions and can be used in pancreatitis as well as to distinguish tumors from inflammation in all cystic formations." (PMID 36128446, 2022). "Vitamin D acts as a negative modulator of TNF-α and IL-6 release, decreasing TNF-α, IL-6, and C-reactive protein (CRP) levels in pancreatitis." (PMID 35631254, 2022). "Therefore, we surmise that TMAO causes the expression of the proinflammatory factors IL-1β, IL-6, and TNF-α to increase significantly by activating the p65 NF-κB pathway, which increases the level of Ca2+ in pancreatic acinar cells, inducing a sensitive state of pancreatitis." (PMID 34925503, 2021). "In pancreatitis as can happen after IRE, various inflammatory mediators are released with concomitant thrombosis, resulting in high levels of IL-6, IL-8 and TNF." (PMID 31684186, 2019). "CID755673 treatment markedly inhibited pancreatic expression of IL-6 and MCP-1 in cerulein-induced pancreatitis." (PMID 29270134, 2017). "Both IL-6 and MCP-1 levels were very low within the normal pancreas, whereas cerulein induced significantly increased IL-6 and MCP-1 in pancreatitis." (PMID 29270134, 2017). "The peak expression of L-1β, IL-6, and TNF-α in the lung tissue occurred at 12 h after the induction of pancreatitis." (PMID 29359164, 2017). "Elevated levels of serum cytokines and chemokines including IL-6, CCL2, and CXCL1 have been reported to be pathological hallmarks of pancreatitis after CVB3 infection." (PMID 27195463, 2016). "Specifically, IL-6, IL-8, VEGF, TGF, IL-10 were not only differentially expressed between PDAC and healthy controls but also between PDAC and pancreatitis patients." (PMID 27170998, 2016). "In the present pancreatitis study, RAI with ATL significantly decreased the content of pro-inflammatory cytokines, such as TNF-α, IL-1β and IL-6." (PMID 25265022, 2014). "In experimental pancreatitis, the plasma levels of TNF-α, IL-1ß, and IL-6 are elevated and their blockade attenuates the disease process." (PMID 23029434, 2012). "Biochemical and immunological assays confirmed that administration of EAE reduced amylase and lipase activity, TNF-alpha, IL-6, MPO activity, and lipid peroxidation which are markers of pancreatitis." (PMID 23008778, 2012). "The production of pro-inflammatory cytokines, including IL-1, IL-6 and TNF-α, has now been shown in the majority of animal models of pancreatitis." (PMID 23181131, 2012). "First, during the acute phase of pancreatitis, ALB production is frequently suppressed as the liver shifts to synthesize acute-phase proteins (e.g., C-reactive protein (CRP)) due to a systemic inflammatory response driven by cytokines (e.g., IL-6)." (PMID 40308642, 2025). "In our study we could verify a release of IL-6 and OSM from pancreatic macrophages under inflammatory conditions, such as pancreatitis." (PMID 40560328, 2025).
pancreatitis (continued). "These investigators suggested that IL-6 and TNF-α have a role in developing pancreatitis." (PMID 38533139, 2024). "Irisin addition in the cer-pancreatitis state resulted in a significant down-regulation of the PPARγ-PGC1α-FNDC5 axis, PPARγ nucleus-translocation and inflammatory state (TNFα and IL-6) in parallel to diminished PL expression and secretion (in vitro and ex vivo models)." (PMID 38927047, 2024). "Although we did not investigate the specific role of IL11 in the immune response in pancreatitis, we found that blocking IL11 signalling had anti-inflammatory effects and reduced IL6, IL1β and TNFα protein levels as well as diminishing NF-κB and STAT3 activation." (PMID 35408908, 2022). "Twelve hours after the caerulein challenge, the pancreas injury index, including serum lipase, α-amylase and inflammatory cytokines, including IL-6 and TNF-α, were significantly upregulated in mice induced with caerulein pancreatitis but decreased significantly after JTE-013 intervention." (PMID 36229875, 2022). "Finally, we added 10umol/l caerulein to AR42J and HPDE6-C7 cells and detected inflammatory factors IL1-beta, IL6, and TNF-alfa after 24 h of intervention confirmed the successful construction of the cell pancreatitis model." (PMID 36611865, 2022). "Therefore, the levels of IL-6, IL-1β, and TNF-α in LPS-induced pancreatitis model in vitro were detected." (PMID 33824873, 2021). "CRP is synthesised in the liver after induction of interleukin-1 (IL-1) and interleukin-6 (IL-6) and it has been used to assess the severity of inflammatory response, The use of CRP in pancreatitis as a marker to assess the course of the disease had been there since the 1980s." (PMID 33564553, 2021). "They found that the IL-6 serum concentrations had sensitivity, specificity, positive predictive value, and negative predictive value for severe or lethal pancreatitis as 80%, 92%, 91%, and 82%, respectively." (PMID 32076577, 2020). "The results suggest that PKD inhibitor could suppress expression of the inflammatory molecule IL-6 and MCP-1 through inhibiting NF-κB activation in pancreatitis." (PMID 29270134, 2017). "Since CRP, PCT and IL-6 had been demonstrated to be elevated by various conditions without infection, i.e., trauma, surgery, burn, pancreatitis, we decided to analyze the subgroup populations." (PMID 27287669, 2016). "In addition, the level of TNF-a and IL-6 in SAP rats increased and reached a peak at 3 h after pancreatitis was induced, then gradually decreased." (PMID 24312352, 2013). "In the patients without post-ERCP pancreatitis, thelevels of IL-4, TNFα, and IL-6 at 24 hours after ERCP were also higherthan those of the basal levels." (PMID 18670651, 2008). "In thepatients with post-ERCP pancreatitis and without pancreatitis, significantlyhigher levels of TNFα and IL-6 were found at 12 hours after ERCP comparedto the levels before ERCP." (PMID 18670651, 2008). "Moreover, another study has reported that PRKD1 mediated NFκB signaling was responsible for controlling inflammatory processes in vivo e.g. immune cell infiltration, inflammation and IL6 release, which were abrogated by employing a PRKD inhibitor in a model of experimental pancreatitis in rats." (PMID 36936923, 2023). "Moreover, emodin could notably decrease the release of pancreatitis markers (amylase and lipase) and inflammatory mediators, such as TNF-α, IL-1β, and IL-6." (PMID 29163548, 2017). "IL-17A delivery in these strains revealed thatneither IL-6 nor signalling via these TNF or IL-1 receptors were required forthe development of pancreatitis: all mice tested developed neutrophil aggregatesand pancreatitis in response to IL-17A in a similar manner." (PMID 26964500, 2016). "We know from prior studies that IL-6 levels in pancreatitis can rise and fall over this time frame and thus the single admission time point may not be representative of the IL-6 response." (PMID 25673030, 2014).